ZC3H18 (zinc finger CCCH-type containing 18)
Synonyms: NHN1
Tractability: PROTAC: UniProt records ubiquitination sites on it; ubiquitination databases record sites on it; its protein half-life has been measured.
Gene: Protein-coding gene on chromosome 16 (88,570,403 to 88,631,964, forward strand). Ensembl gene ENSG00000158545.
Subcellular location: Nucleus
Subcellular location (Human Protein Atlas): Nuclear speckles
Pathways (Reactome):
Metabolism of RNA: Nuclear RNA decay
Gene Ontology:
Molecular function: mRNA cap binding complex binding; protein binding; protein-macromolecule adaptor activity; RNA binding; metal ion binding
Biological process: RNA destabilization
Cellular component: nuclear speck; protein-containing complex; ribonucleoprotein complex; nucleoplasm; nucleus
Genetic constraint (gnomAD): Loss-of-function variants: 6 observed, 93.79 expected, observed/expected ratio (o/e) 0.064, 90% interval 0.034 to 0.13. The upper end of that interval is the gene's LOEUF score, 0.13, which puts it in group 1 of 6, group 1 being the genes least tolerant of losing a copy. Missense variants: 1,226 observed, 1,238 expected, observed/expected ratio (o/e) 0.99, 90% interval 0.94 to 1.04. Synonymous variants: 589 observed, 505.43 expected, observed/expected ratio (o/e) 1.17, 90% interval 1.09 to 1.25.
Homologues: Orthologues: chimpanzee ZC3H18 (99% identical), macaque ZC3H18 (98% identical), mouse Zc3h18 (91% identical), rat Zc3h18 (91% identical), guinea pig ZC3H18 (90% identical), dog ZC3H18 (90% identical), rabbit ZC3H18 (88% identical), pig ZC3H18 (87% identical), tropical clawed frog zc3h18 (63% identical), zebrafish zc3h18 (60% identical), Drosophila melanogaster CG1677 (26% identical), Drosophila melanogaster CG31601 (15% identical). Paralogues in human: PPP1R10 (14% identical), PRR3 (6% identical).
Diseases named in the same sentence as ZC3H18 in open-access papers:
ZC3H18 is named in the same sentence as 21 diseases in open-access papers, as found by Europe PMC text mining. Sharing a sentence is not in itself a finding about the gene and the disease. The quoted sentences say what the papers report.
breast carcinoma (2 papers, 2019 to 2025). "Despite the different roles of E2F1 in ovarian and breast cancer cells, ZC3H18 depletion reduced BRCA1 levels in both cell lines." (PMID 31604914, 2019). "This correlation was also observed in breast cancer, consistent with our observations that ZC3H18 regulates BRCA1 in breast cancer cells." (PMID 31604914, 2019). "Indeed, ZC3H18 depletion enhanced E2F1 binding to DNMT1 in ovarian cancer but not in breast cancer cells, suggesting that loss of ZC3H18 leads to E2F1-DNMT1 repressor complex formation in ovarian cancer cells." (PMID 31604914, 2019). "We next assessed the possibility that ZC3H18 might affect E2F1 and DNMT1 differently in ovarian and breast cancer cells." (PMID 31604914, 2019).
lymphoma (2 papers, 2025). A malignant (clonal) proliferation of B- lymphocytes or T- lymphocytes which involves the lymph nodes, bone marrow and/or extranodal sites. "We now show that ZC3H18 is a key cellular target of EBV that is upregulated in lymphoma lines that exhibit latency I, EBV-transformed cell lines in latency III, and EBV+ DLBCL in latency II/III." (PMID 40354417, 2025). "What causes increased ZC3H18 expression in EBV+ cell lines and lymphomas?" (PMID 40354417, 2025). "In summary, our results demonstrate that STAT3, MYC, and EBNA1 collaborate to regulate the expression of ZC3H18, a protein that is upregulated in EBV+ lymphomas." (PMID 40354417, 2025).
ovarian carcinoma (2 papers, 2019 to 2025). A malignant neoplasm originating from the surface ovarian epithelium. "ChIP of endogenous or overexpressed ZC3H18 demonstrated that ZC3H18 associates with the BRCA1 promoter in multiple ovarian cancer cell lines, raising the possibility that ZC3H18 might affect the binding of transcription factors that regulate BRCA1 expression." (PMID 31604914, 2019). "To address if ZC3H18’s transcription related functions are independent of its replication related functions, we depleted ZC3H18 and assayed the abundance of transcripts of BRCA1, a gene known to be transcriptionally upregulated by ZC3H18 in ovarian cancers." (PMID 40354417, 2025). "Given that ZC3H18 depletion caused BRCA1 promoter methylation and E2F1 recruitment to the BRCA1 promoter, we reasoned that E2F1 might repress BRCA1 expression in ovarian cancer cells by recruiting DNMT1 when ZC3H18 was depleted." (PMID 31604914, 2019). "Here we have identified a key mechanism by which ZC3H18 regulates the BRCA1 promoter by showing that ZC3H18’s ability to bind directly to the BRCA1 promoter and regulate the association of E2F family members is a major driver of BRCA1 expression in ovarian cancer." (PMID 31604914, 2019). "Collectively, these results demonstrate that ZC3H18, a gene located in a chromosomal region frequently deleted in HGSOC, is essential for HR and that ZC3H18 depletion sensitizes ovarian cancer cells to platinum agents and PARP inhibitors." (PMID 31604914, 2019). "Consistent with the RNA-seq analysis, ZC3H18 depletion profoundly decreased BRCA1 mRNA and protein levels in multiple ovarian cancer cell lines and in xenografted OVCAR-8 cells." (PMID 31604914, 2019).
AIDS (1 paper, 2025). A syndrome resulting from the acquired deficiency of cellular immunity caused by the human immunodeficiency virus (HIV). "We further validated this observation in biopsy samples of diffuse large B cell lymphomas (DLBCL) from AIDS patients, again finding a greater abundance of ZC3H18 transcripts in EBV+ compared to EBV- DLBCL." (PMID 40354417, 2025). "In particular, the involvement of EBNA1 may underlie the specific upregulation of ZC3H18 in EBV+ cancer/transformed cell lines and EBV+ DLBCL from AIDS patients." (PMID 40354417, 2025). "We now demonstrate that ZC3H18 expression is upregulated in EBV-transformed and cancer cell lines, as well as in EBV-positive diffuse large B-cell lymphomas from AIDS patients, compared to their EBV-negative counterparts, supporting its activation by EBV." (PMID 40354417, 2025). "With EBV+ AIDS-DLBCL patients continuing to face poorer outcomes compared to EBV- AIDS-DLBCL patients despite antiretroviral therapy and advanced chemotherapeutic regimens, targeting ZC3H18 alongside EBNA1 (or STAT3) may offer greater benefit." (PMID 40354417, 2025).
Alzheimer disease (1 paper, 2022). A progressive, neurodegenerative disease characterized by loss of function and death of nerve cells in several areas of the brain leading to loss of cognitive function such as memory and language. "Gene-based analyses implicated AGXT2 and CALN1 for VL, while analyses of protein-protein interactions implicated synaptic proteins previously associated with Alzheimer disease biology, SYT9 and NRXN1 for VSTM; ZFAND5, GRIK2, and ZC3H18 for VL; and PRLHR for paragraph recall." (PMID 35974141, 2022).
cervical cancer (1 paper, 2025). A primary or metastatic malignant neoplasm involving the cervix. "This study demonstrated that ZC3H18 extensively regulates AS of cancer-associated pathways in HeLa cells and cervical cancer tissues." (PMID 40995431, 2025). "Therefore, the close association between ZC3H18 and cervical cancer highlights its potential as a promising diagnostic and therapeutic target." (PMID 40995431, 2025). "The current study applied the GEO dataset, TCGA dataset, and in vitro experiment to identify the regulation of ZC3H18 on AS in cervical cancer." (PMID 40995431, 2025). "This study aimed to investigate the effect of ZC3H18 on regulating gene expression and AS in cervical cancer and HeLa cells using public datasets and in vitro experiments and help identify the novel targeted therapies to improve the therapeutic efficacy." (PMID 40995431, 2025). "This study aimed to identify the potential effect of zinc finger CCCH-type containing 18 (ZC3H18) in cervical cancer." (PMID 40995431, 2025). "The results showed that ZC3H18-regulated RASEs were correlated with viral processes, DNA replication, and cell cycles in HeLa cells and clinical samples of cervical cancer." (PMID 40995431, 2025). "The database results showed that ZC3H18 was significantly involved in the regulation of RASEs in cervical cancer." (PMID 40995431, 2025). "The identification of ZC3H18-regulated ASEs may provide potential targets for cervical cancer treatment." (PMID 40995431, 2025). "Given that cervical cancer cells with high ZC3H18 expression exhibit significant enrichment in DNA repair pathways, PARP inhibitors may potentially enhance disease control rates in this patient subset." (PMID 40995431, 2025). "We hypothesized that the abnormal expression of ZC3H18 in cervical tissue regulates the variable shear of pre-mRNA and influences the development of cervical cancer." (PMID 40995431, 2025). "Therefore, ZC3H18-regulated RASGs may be involved in tumorigenesis and progression in cervical cancer." (PMID 40995431, 2025). "However, the mechanism by which ZC3H18 functions in cervical cancer remains unclear." (PMID 40995431, 2025). "However, the role of ZC3H18 in the regulation of AS in cervical cancer remains unclear." (PMID 40995431, 2025).
colorectal cancer (1 paper, 2019). A primary or metastatic malignant neoplasm that affects the colon or rectum. "In colorectal cancer cell lines, depletion of ZC3H18 was found to be synthetic lethal with mutant Ras." (PMID 31841561, 2019).
esophageal cancer (1 paper, 2025). A primary or metastatic malignant neoplasm involving the esophagus. "Esophageal cancer cell lines with ZC3H18 knockdown were used to validate the biological role of ZC3H18 in tumorigenesis in vitro and in vivo." (PMID 40070828, 2025). "Bioinformatics analysis of results from the differential gene methylation analysis of 25 patients confirmed that ZC3H18 exhibited significantly lower methylation levels in esophageal cancer tissues (P = 0.0075)." (PMID 40070828, 2025). "Examination of esophageal cancer tissue samples demonstrated overexpression of the ZC3H18 protein, which was positively correlated with adverse prognosis indicators, including tumor differentiation, stage, and invasion depth." (PMID 40070828, 2025). "We generated stable ZC3H18 knockdown and overexpression cell lines in KYSE150 and ECA109 esophageal cancer cell lines and investigated the impact of ZC3H18 modulation on tumor formation in vivo." (PMID 40070828, 2025). "Changes in ZC3H18 expression can significantly affect the tumor biological functions of esophageal cancer cells." (PMID 40070828, 2025). "In conclusion, these findings indicate that the ZC3H18 gene has potential as a novel biomarker for esophageal cancer, with significant potential in the prognosis of the disease." (PMID 40070828, 2025). "ZC3H18 gene exhibits differential methylation in esophageal cancer was positively correlated with unfavorable patient prognosis." (PMID 40070828, 2025). "To further explore the relationship between ZC3H18 and cytokeratins, we conducted multicolor immunofluorescence staining on tissue microarrays derived from esophageal cancer patients." (PMID 40070828, 2025). "ZC3H18 is may become a specific prognostic marker and a potential therapeutic target for esophageal cancer." (PMID 40070828, 2025). "ZC3H18 and multiple keratins were co-localized in esophageal cancer tissue." (PMID 40070828, 2025). "As no previous studies have explored the relationship between ZC3H18 and esophageal cancer, we investigated its expression, function, and potential mechanisms at both tissue and cellular levels." (PMID 40070828, 2025). "Further analysis revealed a significant negative correlation between ZC3H18 expression and its methylation status in esophageal cancer tissues (R = -0.26, P = 0.00076)." (PMID 40070828, 2025).
esophageal tumors (1 paper, 2025). "ZC3H18 plays a critical role in the regulation of biological functions within esophageal tumors." (PMID 40070828, 2025).
glioblastoma (1 paper, 2021). The most malignant astrocytic tumor (WHO grade IV). "Also,ZC3H18,SLIT2 CARF,GPATCH4,CAMK2D,BCORL1,ARHGAP4mutations were found in glioblastoma (T03)." (PMID 34430964, 2021).
ovarian tumors (1 paper, 2019). "Consistent with this possibility, deep ZC3H18 deletions and low ZC3H18 mRNA levels are nearly mutually exclusive with BRCA1 driver mutations and deep deletions in ovarian tumors analyzed by The Cancer Genome Atlas research network." (PMID 31604914, 2019).
squamous intraepithelial lesions (1 paper, 2025). "ZC3H18 is highly expressed in a wide range of tumor tissues, with higher expression in squamous intraepithelial lesions than in normal cervical tissue." (PMID 40995431, 2025).
tumor (5 papers, 2020 to 2025). "Subsequent analysis utilizing the TCGA database revealed that the gene ZC3H18 is aberrantly expressed in tumor tissues and is closely associated with patient prognosis." (PMID 40070828, 2025). "In the neoadjuvant therapy group, ZC3H18 expression was significantly associated with tumor differentiation (P = 0.0146) and tumor depth (P = 0.0007)." (PMID 40070828, 2025). "The results demonstrated that ZC3H18 knockdown significantly inhibited tumor growth, while ZC3H18 overexpression markedly promoted tumor proliferation." (PMID 40070828, 2025). "When combining data from both groups, ZC3H18 expression was significantly correlated with tumor differentiation (P < 0.0001), tumor depth (P < 0.0001), and tumor stage (P = 0.0041)." (PMID 40070828, 2025). "In the surgery-alone group, ZC3H18 expression was significantly correlated with tumor stage (P = 0.0123)." (PMID 40070828, 2025). "We found a greater abundance of ZC3H18 protein in EBV+ tumor and transformed cell lines." (PMID 40354417, 2025). "Moreover, through a complex transcriptional network in which ZC3H18 itself is upregulated by each of these cellular and viral oncoproteins, ZC3H18 then contributes to a feedforward loop to support a tumor promoting environment." (PMID 40354417, 2025). "Firstly, we have not conducted experimental validation to directly examine how ZC3H18 regulates keratin expression, which may, in turn, influence tumor development." (PMID 40070828, 2025). "Six genes—ARHGEF19, CORO1A, ACOT7, ZC3H18, SLC5A5, and ZFAS1—showed statistically significant differential expression between tumor and normal tissues (P < 0.05)." (PMID 40070828, 2025). "Localization analysis revealed that the ZC3H18 protein was predominantly localized within the nuclei of tumor cells in both cancerous and adjacent non-cancerous tissues." (PMID 40070828, 2025). "Given the high expression of ZC3H18 in tumor tissues and its significant negative correlation with patient prognosis, we sought to investigate whether knockdown of ZC3H18 could inhibit tumor growth." (PMID 40070828, 2025).
cancer (3 papers, 2019 to 2025). A tumor composed of atypical neoplastic, often pleomorphic cells that invade other tissues. "Our findings elucidate the mechanisms underlying ZC3H18 upregulation in EBV-cancers and suggest that simultaneously targeting ZC3H18 and its network partners may be of therapeutic interest." (PMID 40354417, 2025). "Functional enrichment analysis showed that ZC3H18-related RASGs are involved in several biological processes, including key cancer-related pathways." (PMID 40995431, 2025). "Future studies should focus on exploring the potential for ZC3H18 as a biomarker or therapeutic target in EBV-driven cancers." (PMID 40354417, 2025). "Given the ability of ZFP91, ZNF503, and ZC3H18 to interact with nucleic acids and their known links to cancer, we focused on the 3 ZFPs." (PMID 31841561, 2019). "The involvement of EBNA1 in this network may explain, at least in part, the preferential upregulation of ZC3H18 in EBV-associated tumors and highlights predictive and therapeutic possibilities for such cancers." (PMID 40354417, 2025). "Thorough investigation of ZC3H18-mediated alternative splicing will enable a more precise understanding of the signaling pathways involved in cancer development and may reveal potential therapeutic strategies targeting ZC3H18." (PMID 40995431, 2025). "Our findings reveal a novel regulatory axis in EBV-positive cancer cells involving STAT3, MYC, EBNA1, & ZC3H18, also linking ZC3H18 to the NF-κB pathway independently of LMP1." (PMID 40354417, 2025). "Given ZC3H18’s roles in RNA processing, transcriptional regulation, and DNA replication, it likely plays a significant role in EBV-related cancers." (PMID 40354417, 2025). "In this study, we reveal that the zinc finger protein ZC3H18, previously identified as a novel component of the cellular replication machinery, is transcriptionally upregulated in EBV-cancers." (PMID 40354417, 2025). "However, our prior research revealed that ZC3H18 is able to interact with nascent/replicating DNA, facilitating replication of the EBV-cancer cell genome." (PMID 40354417, 2025).
infection (2 papers, 2015 to 2023). The state of being infected such as from the introduction of a foreign agent such as serum, vaccine, antigenic substance or organism. "Several infection-induced SUMO targets also are involved in mRNA maturation events, such as 3′ end pre-mRNA processing (CPSF1, CPSF2, FIP1L1, RBBP6, and WDR33), splicing (CLASRP, SFPQ, and ZRANB2), and nuclear RNA quality control (ZC3H18, ZCCHC7, and PAPD5)." (PMID 26549460, 2015).
ZC3H18 also shares sentences with these, for which no sentence is quoted: acute myelogenous leukemia (1 paper); Burkitt lymphoma (1); chronic lymphocytic leukemia (1); diffuse large B-cell lymphoma (1); medulloblastoma (1); myelodysplastic syndrome (1).